PHACTR3 (phosphatase and actin regulator 3)
Synonyms: Scapinin; C20orf101; SCAPIN1; PPP1R123; H17739
Tractability: PROTAC: its protein half-life has been measured.
Gene: Protein-coding gene on chromosome 20 (59,577,495 to 59,847,711, forward strand). Ensembl gene ENSG00000087495.
Subcellular location: Nucleus matrix
Subcellular location (Human Protein Atlas): Nucleoplasm
Gene Ontology:
Molecular function: protein binding; actin binding
Biological process: actin cytoskeleton organization
Cellular component: nucleoplasm; nuclear matrix
Genetic constraint (gnomAD): Loss-of-function variants: 11 observed, 60.21 expected, observed/expected ratio (o/e) 0.18, 90% interval 0.11 to 0.3. The upper end of that interval is the gene's LOEUF score, 0.3, which puts it in group 1 of 6, group 1 being the genes least tolerant of losing a copy. Missense variants: 630 observed, 681.03 expected, observed/expected ratio (o/e) 0.93, 90% interval 0.87 to 0.99. Synonymous variants: 315 observed, 281.25 expected, observed/expected ratio (o/e) 1.12, 90% interval 1.02 to 1.23.
Homologues: Orthologues: chimpanzee PHACTR3 (99% identical), macaque PHACTR3 (98% identical), dog PHACTR3 (91% identical), mouse Phactr3 (89% identical), pig PHACTR3 (88% identical), rabbit PHACTR3 (88% identical), rat Phactr3 (84% identical), guinea pig PHACTR3 (76% identical), tropical clawed frog phactr3 (66% identical), zebrafish phactr3b (55% identical), zebrafish phactr3a (50% identical), Drosophila melanogaster CG32264 (33% identical), and 1 more. Paralogues in human: PHACTR1 (40% identical), PHACTR2 (33% identical), PHACTR4 (32% identical).
Diseases named in the same sentence as PHACTR3 in open-access papers:
PHACTR3 is named in the same sentence as 12 diseases in open-access papers, as found by Europe PMC text mining. Sharing a sentence is not in itself a finding about the gene and the disease. The quoted sentences say what the papers report.
bladder cancer (2 papers, 2020 to 2022). "The urinary methylation levels of FAM19A4, GHSR, MAL, miR-129, miR-935, PHACTR3, PRDM14, SST and ZIC1 were significantly higher in patients with bladder cancer than in controls (all, p < 0.001)." (PMID 35123558, 2022). "All nine urinary methylation markers (FAM19A4, GHSR, MAL, miR-129, miR-935, PHACTR3, PRDM14, SST and ZIC1) showed significantly higher methylation levels in bladder cancer patients than in controls (p < 0.001)." (PMID 35123558, 2022). "These encompass seven protein-coding genes (FAM19A4, GHSR, MAL, PHACTR3, PRDM14, SST and ZIC1)—of which, the CpG islands are methylated in bladder cancer—as well as two miRNAs (miR-129 and miR-935) with promoter regions that are also known to be methylated in bladder cancer." (PMID 32252299, 2020).
lung carcinoma (2 papers, 2017 to 2023). "PHACTR3 is mainly expressed in the brain and lung and is associated with the development of lung cancer." (PMID 37723557, 2023).
Obesity (2 papers, 2018 to 2023). Accumulation of substantial excess body fat. "SWIF(r) also identified SNPs within three other genes (PDGFRA, SIDT2, and PHACTR3) that have previously been associated with obesity and metabolism phenotypes." (PMID 29459739, 2018). "The Venn diagram showed that there are indeed common DEGs between obesity and asthma, namely IL36RN, PHACTR3, SLAMF7, AKR1B10 and RNF182." (PMID 37723557, 2023).
cervical cancer (1 paper, 2019). A primary or metastatic malignant neoplasm involving the cervix. "At the threshold corresponding to 80% specificity in controls, all 6 DNA methylation markers revealed a high sensitivity varying from 76% (FAM19A4 and PHACTR3) to 83% (PRDM14 and ZIC1) for cervical cancer detection in urine sediments." (PMID 30816167, 2019).
leukemia (1 paper, 2014). A malignant (clonal) hematologic disorder, involving hematopoietic stem cells and characterized by the presence of primitive or atypical myeloid or lymphoid cells in the bone marrow and the blood. "Phactr3 was originally named as the nuclear scaffold-associated PP1-inhibiting protein (scapinin), which is found in the nuclear insoluble fraction of the leukemia cell line HL-60." (PMID 25405772, 2014).
rectal adenoma (1 paper, 2012). "Array CGH found that copy number increase of GPNMB (7p15.2), OXGR1 (13q32.1), C13orf27 (13q32.2-q34), PMEPA1 (20q13.31), PHACTR3 (20q13.32) and decrease of SMAD4 (18q21.2), BCL2 (18q21.33) occurred in both rectal adenoma and carcinoma." (PMID 23158542, 2012).
rectal cancer (1 paper, 2016). A primary or metastatic malignant neoplasm that affects the rectum. "Ten of the 36 (EYA4, FOXI2, CNRIP1, SFRP1, ADHFE1, C2orf40, MAL, PHACTR3, SST, TMEFF2) were known as rectal cancer related genes with aberrant methylation." (PMID 27566576, 2016).
tumor (3 papers, 2009 to 2025). "For urine supernatant, there was a significant correlation between methylation levels of MAL, PHACTR3, PRDM14, SST and ZIC1 and the matched tumor tissues." (PMID 32252299, 2020).
PHACTR3 also shares sentences with these, for which no sentence is quoted: cancer (2 papers); aneurysm (1); Anorexia (1); asthma (1).